CCND1 (cyclin D1)
Diseases named in the same sentence as CCND1 in open-access papers (continued):
Sharing a sentence is not in itself a finding about the gene and the disease.
cancer (continued). "Concurrent with these observations, we could demonstrate a significant reduction in expression of the G1 phase cyclin, cyclin D1, in PS1 cells, but not cancer cells, upon FGFR inhibition." (PMID 24503018, 2014). "Furthermore, an anti-AGR2 therapy, unlike fulvestrant, can potentially function in cancers driven by cyclin D1 that can no longer respond to E2, given the ER-independent actions of AGR2 on cyclin D1." (PMID 20525379, 2010). "CCND1 protein was downregulated by hypoxia in all the nonrenal cell lines examined including cells derived from lung (A549), cervical (HeLa), or breast (HBL100, ZR-75-1,T-47D) cancers." (PMID 15026807, 2004). "Thus, critical for regeneration without cancer initiation, robust proliferation responses result from a YAP-induced and receptor-mediated prolonged increase in the cyclin D1/p27 ratio, which is reversed by delayed suppression of receptor signaling after contact inhibition of YAP." (PMID 41611993, 2026). "Another study with patient-derived organoids model revealed that the oligomeric proanthocyanidins combined to the curcumin attenuated the expression of cyclin D1, PCNA, and HSPA 5, which could serve as a method that preferentially targets cancer cells without affecting normal cells." (PMID 36776331, 2023). "To confirm whether the negative correlation was observed in other cancer types, we obtained proton RBE values (relative to 60Co gamma-ray) of 17 human NSCLC cell lines from a previously published study and found a similar negative correlation between CCND1 mRNA and proton RBE (r = −0.55, p = 0.010)." (PMID 31591311, 2019).
infection (77 papers, 2009 to 2025). The state of being infected such as from the introduction of a foreign agent such as serum, vaccine, antigenic substance or organism. "Genes linked to STAT3 during infection were associated with GO terms such as regulation of cell proliferation (CCND1, JUNB), negative regulation of apoptosis (MCL-1, NFKB1), cytokine-mediated signaling pathway (IL10RA, SOCS1), and immune system process (CRK, IRF9)." (PMID 41115066, 2025). "Septic infection caused a significant upregulation of cyclin D1 expression by marrow cells." (PMID 38665923, 2024). "Overexpressing cyclin D1 alone through AAV7m8-GFAP-cyclin D1 infection stimulated a subset of MG cells to proliferate, resulting in a threefold increase in the number of EdU+ MG cells compared to p27Kip1 knockdown." (PMID 40178080, 2025). "The CCND1 gene is much less expressed with heat-inactivated bacteria, suggesting that activation of this gene requires infection of cells by live bacteria." (PMID 37285354, 2023). "The infection resulted in a 77-fold decrease in miR-503 expression in ECs, where miRNA-503 regulates the expression of cyclin D1." (PMID 36380817, 2023). "In the infected control group (GIII), on the 20th and 100th day post-infection, moderate and marked positive nuclear expression of cyclin D1 was detected, respectively." (PMID 37375825, 2023). "At day 1 post-infection, cyclin D1 expression was increased in HEMC-HCMV-DB (p-value(HCMV-DB: HMEC-UI) = 0.03) compared to HMEC-HCMV-TB40/E (p-value(HCMV-TB40/E: HMEC-UI) = 0.06)." (PMID 35003089, 2021). "On the other hand, we found that HIV-1-infected macrophages (7 days of infection) presented higher expression of Cyclin D1 and that both neuropeptides diminished the total levels of this protein in infected cells." (PMID 29951068, 2018). "Over-expression of Cyclin D1, telomerase, and Bmi-1 belonging to the polycomb family of proteins, encourages the immortalization of nasopharyngeal epithelial cells, which upon infection in vitro can be selected for latent outgrowths." (PMID 29561768, 2018). "Endogenous mmp2, mmp7, mmp9, DKK-1, c-myc and CCND-1 mRNA and β-catenin protein expression levels were detected in P1-infected ST cells at 24, 48, and 72 h post-infection and compared with those in uninfected cells." (PMID 29593670, 2018). "Consistent with this possibility, we did observe that HIF-1α silencing augmented Cyclin D1 mRNA after infection." (PMID 28401064, 2017). "Ninety-six hours after infection, total RNA was subjected to real-time RT-PCR to compare the levels of CCND1 mRNA." (PMID 29199958, 2017). "Upon the infection of Ad5-AlncRNA, the phosphorylation of mTOR, GSK3β, S6K and 4EBP1 was reduced, sequentially p27 expression was increased while cyclin D1 expression was reduced." (PMID 27689326, 2016). "Accordingly, except the G1-specific Cyclin D1, cell cycle factors were barely detectable at the time of infection." (PMID 25393019, 2014). "To further define the disruption in the cell-cycle of GNPCs following infection we assayed the levels of two cyclins, cyclin D1 and cyclin B1, in control and MCMV infected mice." (PMID 23505367, 2013). "Silencing of OCT4 expression by OCT4-shRNA resulted in the down-regulation of CCND1 expression in Hep3B cells, whereas enhanced OCT4 expression by Ad5-OCT4 infection led to an up-regulation of CCND1 expression in BEL-7404 cells." (PMID 23433354, 2013). "Increased Cyclin D1 expression was observed at days 8 (∼2.07-fold) and 30 (∼1.41-fold); it then decreased under the baseline from day60 to 360 post-infection." (PMID 22253905, 2012).
infection (continued). "Cyclin D1 mRNA expression was increased from day2 (∼1.41-fold) to 30 (∼2.34-fold); then it decreased under the baseline from day 60 to 360 post-infection." (PMID 22253905, 2012). "To exclude this possibility, we reactivated both myotubes and quiescent fibroblasts by infection with the mutant adenovirus, dl520, or expression of cyclin D1 and cdk4." (PMID 20644635, 2010). "The results indicated that, with the replication of the MDV RB1B strain, the expression level of Wnt/β-catenin signaling pathway-related genes β-catenin, TCF4, LEF1, c-Myc, and Cyclin D1 were significantly downregulated after 24 h of RB1B strain infection and significantly upregulated at 60 h." (PMID 38638910, 2024). "Mcm2 and Cyclin D1 were amplified in c-Junf/f mice as well as in c-JunΔli mice upon infection." (PMID 37990129, 2023). "In addition, A. muricata decreases the expression of cyclin D1 in early and late infection and can be used as a prognostic marker in the case of colorectal dysplasia." (PMID 37375825, 2023). "We tested the hypothesis that the cellular proliferation response may arise from rapid B cell or T cell expansion in response to infection by evaluating the correlation between the CCND1 module and expression of validated cell-type-specific signatures." (PMID 35474751, 2022). "The increase of CCND1 in KO male mice in response to infection may benefit LAC growth and G1-S phase progression, and decreased expression of CCND1 in female mice may contribute to the inhibition of cellular proliferation by a mechanism yet to be defined." (PMID 35844510, 2022). "Also, the infection with lenti-si-SLC34A2 decreased the expression of cyclin D1, which is the target gene of EZH2." (PMID 30038060, 2019). "After infection with H. pylori strains, qRT-PCR results indicated a significant decrease of mRNA expression of CCND1 (p < 0.001 for both J166 and 7.13 strains) and c-MYC (p < 0.01 and p < 0.001 for J166 and 7.13 strains, respectively) in TFF1 expressing cells as compared to control cells." (PMID 25980439, 2015). "Interestingly, in HeLa cells infected with LCMV, cyclin D1 was down-regulated during the first 24 hours after infection but increased dramatically at a later stage of the infection." (PMID 25822203, 2015). "Levels of cyclin D1 were not significantly different between control or infected animals, suggesting that infection with MCMV did not alter the signals associated with entry of GNPCs into G1 (data not shown)." (PMID 23505367, 2013). "Additionally, in cocultured GC cells with an infection from H. pylori, cyclin D1 is up-regulated." (PMID 37594635, 2023). "The overwhelming majority of changed miRNAs were downregulated after infection and infection plus SP-A2 (1A0) protein rescue, and these were predicted to target genes that play a role in cell cycle and growth and proliferation pathways, such as CCND1, CCND2, CDK7, CDKN2A, E2F1, E2F2, E2F3, and MYC." (PMID 35844510, 2022). "Interestingly, infection activates the Notch pathway which regulates the expression of cyclin D1." (PMID 19644556, 2009). "The upregulation of the Wnt target gene expression, including Axin2, EPHB2, CCND1, CD44, TERT, and MYC in PEDV-infected cells, further highlights the activation of WNT signaling in response to infection." (PMID 40396761, 2025). "In contrast, other Wnt-induced targets (CCND1, FN1, MCT1, MYC) were significantly downregulated by the infection." (PMID 38584257, 2024). "This infection led to upregulation of GSK-3β level and reduction in the active β-catenin protein level, which subsequently reduce the level of cyclin-D1." (PMID 37861335, 2023).
infection (continued). "In cultured VSMCs, treatment with PGE1-OH or infection of Ad-EP4 also significantly upregulated the mRNA levels of genes related to cell proliferation including Ki67, Foxm1, Ccna2, Ccnb1, Ccnd1, Ccnd2, Ccne1, and CDK2." (PMID 36078128, 2022). "Another recent study has shown that infection of HOK cells with S. aureus can facilitate increased cell proliferation through upregulation of COX2 and a concomitant increase in cyclin D1 with a suppression of p16." (PMID 35269394, 2022). "This analysis revealed that STAT3 itself, and its targets such as CCNB1 and CCND1, were significantly downregulated in Hs 578T and MDA-MB-231 TNBC cells following shNONO infection." (PMID 32724453, 2020). "Since efficient cell growth requires double infection with mutant CDK4 and Cyclin D1-expressing lentiviruses, an estimated 64% of cells would be doubly-infected, while the rest (∼36%) would have a single transgene, mutant CDK4 or Cyclin D1." (PMID 32269992, 2020). "In a previous study, we showed that infection of gastric cells with H. pylori induces HIF-1α protein levels, which in turn coincided with a decrease in Cyclin D1 half-life and alterations in the cell cycle." (PMID 31185594, 2019). "Coincidentally, Cyclin D1 is over-expressed in NPC tumors and promotes the stable outgrowth of EBV-infected epithelial cell clones upon de novo infection in vitro." (PMID 29561768, 2018). "Ninety-six hours after infection, total RNA was extracted and the transcript levels for LAST, CCND1, CCNE1, CDK2, CDK4 and c-Myc were analyzed by real-time RT-PCR." (PMID 29199958, 2017). "The up-regulation of cyclin D1 expression was observed with HCMV strains AD169 and HCMV-DB after one day post-infection and was sustained up to 6 days post-infection." (PMID 23555719, 2013). "Although cyclin D1 is known to be a target gene of EGFR and STAT3, its transcriptional regulation remains elusive after the infection of virus." (PMID 24499623, 2013). "Western blot analysis of total protein extracts revealed that although cyclin-D1 levels were unaffected, both MAD2 and Skp2 levels were diminished in alveolar macrophages upon in vivo infection." (PMID 22396644, 2012). "Infection with STAT3-shRNA reduced the mRNA levels of ROR1 and the Stat3-regulated genes STAT3, Bcl2, Bcl-XL, Cyclin D1, c-Myc, WAF1/p21, and Pim1." (PMID 20686606, 2010). "In infected cultured adipocytes, we demonstrated that infection resulted in a reduction in the expression of caveolin-1 and activation of ERK; both of these events increase the expression of cyclin D1." (PMID 19644556, 2009). "The results showed an increase in the proportion of stem cells in the S and G2/M phases, upregulation of proliferation-related genes, and activation of the Wnt pathway, evidenced by the elevated expression of Wnt target genes such as AXIN2, EPHB2, CCND1, CD44, TERT, and MYC following infection." (PMID 40396761, 2025). "Accordingly, infection of L6E9 myoblasts by the Brazil strain led to no significant alteration of cyclin D1 promotor activity or cyclin D1 protein stability in infected cultures." (PMID 32626662, 2020). "The levels of cyclin D1, mmp7 and mmp9 mRNA in livers and spleens of the P1 infection group did not change significantly, but significantly decreased in kidneys and livers compared with those in the mock infected group." (PMID 29593670, 2018). "Unlike with 293 cells, de novo infection of nasopharyngeal cell lines is inefficient and requires the expression of cyclin D1 to encourage the outgrowth of EBV-infected clones." (PMID 29134204, 2017). "Our results revealed that infection did not reduce the transcription of Cyclin D1 in either of the stably transfected cell lines." (PMID 28401064, 2017). "Our results showed that infection in the presence of MG132 and CHX partially restored Cyclin D1 levels compared to the treatment with CHX alone, suggesting that Cyclin D1 decrease mediated by H. pylori infection is attributable in part to degradation via the proteasome." (PMID 28401064, 2017).
infection (continued). "There was no significant change to Cyclin D1 level throughout the infection, except at 28 dpc, when it was down-regulated compared to uninfected ileums (p<0.01)." (PMID 28323899, 2017). "Quantitative real-time RT-PCR (qRT-PCR) analysis was used to measure the mRNA expression levels of β-catenin, cyclin D1, Dvl, LRP5, or matrix metalloproteinase-7 (MMP7) after infection with RVFV MP12 or RVFV MP12-GFP (MOI of 1) or treatment with Wnt3A in A549 cells." (PMID 27226375, 2016). "In addition, we determined expressions of CCND1, CCND2, CCNE1 and pRb in rat hypertrophic myocardium after 2-week infection with recombinant miR-16 adenovirus." (PMID 25583328, 2015). "LCMV-WE also induced expression of cyclin D1, especially at day 8 after LCMV-WE infection of mice." (PMID 25822203, 2015). "As for WT (KN99α) C. neoformans, the acapsular strain (cap59D), which also induced cell cycle alteration and aneuploidy, led upon infection to decreased levels of MAD2, cyclin-D1 and Skp2, in contrast to serotype D strain (JEC21), which had no impact on the levels of these proteins as expected." (PMID 22396644, 2012). "However, in response to infection, male mice exhibited higher expression levels of CDKN1B, and CTNNB1 (KO, 1A3), TCF4 (1A0, 6A2), TAP1, and TAP2, (1A0), CDKN1A, (1A3, 6A2), MARCO, and MMP12 (1A3), CCND1, CDK2, IRF and MYC (6A2) compared to females." (PMID 32670284, 2020). "We found that infection with Jad/C(4fC) resulted in the significant upregulation of c-MYC (P < 4 × 10−6), TBX3 (P < 0.0006), AXIN2 (P < 0.0068), FNDC3B (P < 1 × 10−5), FASN (P < 0.0005) and CCND1 (P < 0.0002), with c-MYC and TBX3 showing the highest upregulation levels." (PMID 30046100, 2018). "In the present study, we could confirm the induction of p-ERK1/2 and a parallel expression of Cyclin D1 and PCNA from the beginning of infection and their persistence during the progression of E. multilocularis growth in the liver during the first 2 stages of parasite development." (PMID 22253905, 2012). "For example, cyclin D1, an important factor for initiation of DNA synthesis, was not significantly affected by LCMV-ARM at day 8 after infection, but was induced by LCMV-WE." (PMID 25822203, 2015).